VIM (vimentin)
Diseases named in the same sentence as VIM in open-access papers (continued):
Sharing a sentence is not in itself a finding about the gene and the disease.
tumor (continued). "CLDNs, along with E- and N-cadherins and vimentin, are frequently dysregulated in cancer and are also known as potent regulators of EMT, tumor invasion, and tumor stemness, which are fundamental factors contributing to tumor resistance to chemotherapy." (PMID 40943068, 2025). "CD27 showed coexpression with scattered vimentin + CAFs (arrow) and CD3 + T-cells (arrows) in the stroma, and with a moderate number of CD68 + TAMs in the stroma compartment and inside tumor nests (arrows)." (PMID 40205178, 2025). "Tumour cells expressed vimentin, S-100 and NSE and were negative to CD3, CD20, CD79a, MHC II, MUM1, desmin, c-Kit, pancytokeratin and α-SMA." (PMID 40045318, 2025). "Subsequently, tumor formation experiments in nude mice revealed that NSUN5 KO significantly reduced SMAD3 and p‐SMAD3 levels in tumors, accompanied by an increase in E‐cadherin (an epithelial marker) and a decrease in vimentin (a mesenchymal marker)." (PMID 39531371, 2025). "Additionally, N1ICD overexpression upregulated the EMT marker VIM to a greater extent than N2ICD overexpression, suggesting distinct roles for NOTCH1 and NOTCH2 in regulating EMT and tumor-intrinsic STING expression." (PMID 40627448, 2025). "The tumor cells demonstrated strong positivity for CD99 (also known as MIC-2), a cell surface glycoprotein that typically exhibits a characteristic membranous pattern, and for vimentin, a cytoskeletal protein." (PMID 41281128, 2025). "Also, the expression of the mesenchymal marker Vimentin, along with multiple microenvironmental cues within the SGACC tumor, suggests the initiation of a mesenchymal transition program (MTP)." (PMID 40950184, 2025). "Additionally, the tumor's immunohistochemical positivity for SMA and vimentin further corroborated its glomus cell origin." (PMID 40225461, 2025). "We assessed circulating tumor cell subsets expressing cancer stem cell markers (CD90, epithelial cell adhesion molecule, CD133, vimentin) using multiparametric flow cytometry at early and maximal response phases in patients receiving atezolizumab plus bevacizumab or lenvatinib." (PMID 40940925, 2025). "Therefore, PBRM1 is a critical determinant of tumor grade, EMT, and metastasis in PDAC and functions by directly regulating vimentin expression." (PMID 40454484, 2025). "Importantly, we provided direct experimental support: silencing MIR4435-2HG impaired tumor proliferation, migration, invasion, and reversed EMT and immune evasion phenotypes (upregulation of E-cadherin; downregulation of Vimentin and PD-L1)." (PMID 40843374, 2025). "Carcinomatous differentiation was characterized by islands and trabecules of polygonal cytokeratin AE1/AE3-positive and p63-, cytokeratin 14-negative, SMA-negative, and vimentin-negative tumor cells with moderate anisocytosis and anisokaryosis." (PMID 40509039, 2025). "Similarly, tumor tissue from mice bearing sh-PTGDS cells displayed decreased expression level of c-myc, CDK4, vimentin and Ki67, and increased expression level of Bax and cleaved PARP." (PMID 39706989, 2025). "The results demonstrated that knockdown of ESRRG downregulated PCNA, MMP-2, VIMENTIN, and N-cadherin, while upregulating E-cadherin expression, suggesting that ESRRG may promote tumor migration and invasion by modulating EMT." (PMID 40356747, 2025). "The observed S-100 positivity and vimentin negativity in this case expand the known immunophenotypic spectrum of UESL, underscoring the potential for unexpected immunohistochemical heterogeneity within this tumor entity." (PMID 41479796, 2025). "Strikingly, immunohistochemical double staining of ADAMTS13 and vimentin in human PDAC tissues revealed co‐expression of ADAMTS13 and vimentin in tumor cell clusters with an invasive solid, trabecular growth pattern, while vimentin was absent in glandular tumor structures and precursor lesions." (PMID 41211185, 2025). "The tumor was positive for CD34, CD117, and vimentin, with a low MIB-1 index." (PMID 40507589, 2025).
tumor (continued). "Tumour cells showed cytoplasmic expression of vimentin and were negative to desmin, α-SMA, S-100 and c-Kit." (PMID 40045318, 2025). "Immunohistochemical analysis showed that the tumor cells of inflammatory myofibroblastoma strongly expressed vimentin, partially expressed desmin and ALK, and showed no expression of CD34 and CD117." (PMID 40548121, 2025). "Vimentin, beyond its role as an EMT marker, actively promotes EMT and tumor progression in vivo." (PMID 40618999, 2025). "The Western blot analysis of vimentin protein levels in the mixed culture (passage 1) and SCC25-E cells showed a tendency toward downregulation, which supports the epithelial character of the CAF-influenced tumor cells compared to the control (SCC-25)." (PMID 40002772, 2025). "These tumour cells are immunohistochemically positive for S-100 protein (supporting the neural origin of granular cell tumour), as well as for neuron-specific enolase, CD68, calretinin, CD57, inhibin, TFE3, SOX, CD59, PGP9.5, and vimentin." (PMID 40256332, 2025). "Subsequently, Western blot analysis of tumor tissue lysates from A549-BRG1 tumors revealed reduced pEGFRTyr1068, EGFR, and vimentin expression, which was further attenuated following gefitinib treatment (p < 0.05), relative to their expression levels in gefitinib- and DMSO-treated A549-Puro tumors." (PMID 41514577, 2025). "Consistent with these in vitro findings, analysis of xenograft tumor tissues revealed a similar downregulation of COX2, iNOS, Vimentin, and Slug, together with an upregulation of Bax and suppression of Bcl2, further supporting the induction of mitochondria‐mediated apoptosis by FPHPE." (PMID 41200213, 2025). "Additionally, we performed mIF on tumor tissues from LACC patients, using antibodies against IL1R1, p16, and vimentin." (PMID 39903771, 2025). "Clinically, vimentin R64 aDMA status correlates significantly with advanced tumor stage and poor survival in triple‐negative breast cancer (TNBC), establishing this modification as a robust prognostic biomarker for metastatic risk." (PMID 40884268, 2025). "Finally, the remaining nine mice tumor specimens were processed for histological examination via standard hematoxylin and eosin (HE) staining and also examined for EMA, vimentin, and Ki‐67 (as detected by MIB‐1 antibody) via immunohistochemical (IHC) staining." (PMID 39996452, 2025). "In addition, compared with those in the control group, we observed reduced expression of E-cadherin, increased expression of vimentin, β-catenin, elevated levels of VEGF, and an increase in the number of CD31+ microvessels in tumor tissues." (PMID 40624028, 2025). "Comparatively, while strong stromal staining for vimentin was observed in all cases, no positive staining of tumour cells (score > 0) was observed in any of the primary or metastatic cases." (PMID 41105300, 2025). "In this case, spindle and stellate tumor cells were strongly positive for vimentin and CD34, and negative for CK, desmin, SMA, HMB-45, MDM2, CDK4, p16, β-catenin, and STAT6." (PMID 41458523, 2025). "Vimentin also interacts with key EMT signaling pathways, such as TGF-β, to drive tumor invasion." (PMID 40618999, 2025). "Notably, we observed increased expression of tissue-residence markers (ITGA1, VIM, LGALS1) also in proliferating blood NKs, indicating their inclination toward blood-tumor migration." (PMID 40164596, 2025). "miR‐498 appears to regulate the truncation of Vimentin into VIM3, which in turn may promote tumor invasiveness through alterations in cytoskeletal organization." (PMID 40457691, 2025). "Vimentin, a marker of epithelial-to-mesenchymal transition (EMT), is more commonly associated with the basal-like subtype, but there is possibility for presence the both vimentin-positive and vimentin-negative cells in one tumor." (PMID 40805153, 2025).
tumor (continued). "Similarly, tumor tissue from mice treated with AT56 displayed decreased expression of c-myc, CDK4 and vimentin, and increased expression of cleaved PARP and Bax." (PMID 39706989, 2025). "Their IHC profile includes diffuse vimentin and focal SMA expression in the tumor cells." (PMID 39497877, 2024). "The immunohistochemical staining results of the xenografted tumor tissues revealed that ECM proteins treatment significantly increased the expression levels of VM and EMT‐related markers, including VE‐cadherin, EphA2, and Vimentin." (PMID 39036079, 2024). "The tumor presented as atypical spindle cells expressing vimentin and CD10, but without expression of epithelial markers (cytokeratin AE1/AE3, cytokeratin 8/18, desmin)." (PMID 39594178, 2024). "Immunohistochemically, these tumor cells show diffuse reactivity for cytokeratin and vimentin localized to the cytoplasmic inclusions, but not for desmin, smooth muscle actin, or other skeletal muscle markers." (PMID 39677213, 2024). "IHC examination revealed tumour cells positive for CK, P40, P63 and Vimentin and negative for CD31, CD34, S100 and HMB45." (PMID 39816396, 2024). "The tumor cells typically form nests and exhibit positive staining for S-100, HMB-45, and vimentin." (PMID 39588214, 2024). "We examined their unique cell morphology characteristics (A) and analyzed a wide range of tumor markers (B), including the PD‐1/PD‐L1 status, PD‐L2 expression, EMT markers (vimentin, E‐cadherin, and N‐cadherin), oncogenes (TWIST and Snai1), and the HNC stem cell marker CD44." (PMID 38103190, 2024). "On immunohistochemical evaluation, tumor cells were positive for vimentin, smooth muscle actin, and desmin and negative for CD117, DOG1, and CD34." (PMID 39280874, 2024). "Immunohistochemistry revealed partially preserved cytokeratins, especially cytokeratin 5, with carcinoma cells being vimentin negative and tumor stroma vimentin positive." (PMID 39463382, 2024). "In the ALDH18A1 knockdown group, the protein expression of two well-known EMT-related genes (N-cadherin and Vimentin) and the Epithelial mesenchymal transition (EMT) transcription factor Snail1 decreased, suggesting its suppression of EMT and reduction of tumor cell migration properties." (PMID 38970690, 2024). "Tumor cells were positive to vimentin and CD99, but negative to S-100, SMA, HHF-35, desmin, CD31, CD34, STAT-6 and pan-cytokeratin (AE1/AE3)." (PMID 39462411, 2024). "Moreover, ZN444B treatment induces P21 expression and decreases vimentin expression, implying that FOSL2 is involved in tumor progression and metastasis." (PMID 39010083, 2024). "Analysis of the IHC cohort showed positive correlations between Slug, Twist1, or vimentin expression and PD-L1 expression and a negative correlation between E-cadherin expression and PD-L1 expression by tumor cells in patients with PD after ICI therapy." (PMID 38729997, 2024). "Similarly, changes in the distribution patterns of vimentin in the control tumors, which only labels myoepithelial cells, and in the tumors over-expressing SEMA3F, which is widely distributed in the tumor mass, have been observed." (PMID 39138514, 2024). "This tumor generally expresses CK, calretinin, inhibin, CD10, and vimentin." (PMID 39351365, 2024). "In addition, the overexpression of AKT3 also increased the expression of vimentin, indicating that AKT3 promotes tumor cell migration." (PMID 38491196, 2024). "According to previous studies, vimentin expression is upregulated during EMT in OC, and blocking vimentin expression leads to the re-epithelialization of cells undergoing EMT and attenuates the invasive ability of tumor cells." (PMID 38879666, 2024). "Immunohistochemical analysis demonstrated the positive expression of S100A4, CDK4, MDM2, CD34, and Vimentin, along with the negative expression of Leptin, confirming the tumor’s high aggressiveness and malignancy." (PMID 39591300, 2024).
tumor (continued). "On immunostaining, the tumour cells showed strong expression of calretinin, inhibin, vimentin, WT-1 and oestrogen receptor (ER) and were negative for cytokeratin 7 (CK7), and epithelial membrane antigen (EMA)." (PMID 38376618, 2024). "Immunohistochemically, the tumor cells tested positive for desmin, vimentin, SMA, and CD34 and negative for S-100 and CK." (PMID 38590660, 2024). "Tumor cells tested positive for α-smooth muscle actin (SMA) and vimentin." (PMID 39130873, 2024). "The pathology showed the tumor cells to be positive for cytokeratin (CK), Vimentin, EMA, CD34, cyclinD1, negative for CK8, CK19, CK20, SMA, Desmin, S-100, CD117, Dog-1, Hepar-1, SOX-10 and ALK, and Ki-67 approximately 50%, which confirmed the diagnosis of SHC." (PMID 38552058, 2024). "Tumor cells in case 3 of our study were positive to vimentin and CD99 but they were negative to S-100, desmin, HHF-35, SMA, CD31, CD34, STAT-6 and pan-cytokeratin (AE1/AE3)." (PMID 39462411, 2024). "Overexpression of IL-15 upregulated the expression of vimentin, a biomarker of mesenchymal-phenotype tumor cells, but did not affect the expression of E-cadherin, a biomarker of epithelial-phenotype tumor cells." (PMID 38637902, 2024). "Additionally, the expression of EMT markers was analyzed using IHC of tumor tissue sections, and the PROX1 knockdown tumors were discovered to exhibit lower expression of vimentin and induced expression of E-cadherin." (PMID 38244581, 2024). "Immunohistochemistry on tumor specimens from in vivo experiments also suggested that in the low-expression METTL3 group, both subcutaneous tumors and lung metastases showed significantly reduced expression of VIM and SNAIL proteins." (PMID 38605400, 2024). "miR-18a/antagomiR tumours showed a higher proportion of cells co-expressing Vimentin and E-cadherin when compared to negative control tumours." (PMID 38786043, 2024). "Immunofluorescence staining was performed on the tumour sections from the miR-18a/antagomiR tumours and the antagomiR negative control tumours for the markers Vimentin and E-cadherin." (PMID 38786043, 2024). "Additionally, the tumor was positive for CK5, AE1/AE3+CK8/18, p63, vimentin, E-cadherin, and synaptophysin, while estrogen receptor staining was negative." (PMID 39765541, 2024). "This fibroblast‐like transformation of tumor cells is distinct from EMT that promotes tumor malignancy, as the related markers E‐cadherin and Vimentin showed no significant changes after TM treatment." (PMID 39206698, 2024). "Suppression of fibronectin, vimentin, N-cadherin, MMP-9, MMP-2, twist, and snail.↑ Epithelial markers E-cadherin and Occludin levels.↓ Migratory and invasive potential of tumor cells by reversing epithelial-to-mesenchymal transition (EMT). ↓ PI3K/Akt/mTOR activation." (PMID 38611719, 2024). "Additionally, the tumor cells were strongly positive for CD56 and INI-1, and partially positive for CD99 and vimentin." (PMID 39399175, 2024). "Other immunohistochemical markers that may be focally positive and heterogeneous in tumor cells include desmin, CD68, vimentin, glypican‐3, and CD10, whereas myogenin, S‐100 protein, CD117, and HepPar 1 should be negative." (PMID 39587653, 2024). "Conversely, ANGPTL4 inhibition significantly repressed the tumor weight and volume of SKOV3 cells with low vimentin, PCNA, MMP9, ESM1 and CD34 expression in comparison with the vector and NC groups, which could also be rescued by Colivelin." (PMID 38212795, 2024). "Furthermore, we examined the expression of several most well-known EMT-related genes (N-cadherin, SNAI1, Vimentin) and observed that ALDH18A1 knockdown suppressed the EMT process, indicating a reduced capacity for tumor migration." (PMID 38970690, 2024). "Subsequently, a decrease in E-cadherin and an increase in N-cadherin and vimentin was observed after over-expressing LINC01133, confirming that LINC01133 could enhance tumor EMT in PDAC." (PMID 38987572, 2024).
tumor (continued). "Typically, tumor cells show positivity for vimentin, SMA, and H-caldesmon, while being negative for S-100 protein and c-KIT, supporting the diagnosis of PF." (PMID 38732067, 2024). "On immunohistochemical analysis, the tumor was positive for desmin, muscle actin, beta-catenin, and vimentin and negative for CD1 (c-kit), DOG1, S100, CD117, and Ki-67." (PMID 38846219, 2024). "On immunostaining, the tumour cells expressed inhibin, calretinin, vimentin, ER, WT1 and CK7 and were negative for EMA." (PMID 38376618, 2024). "Simultaneously, western blot results also showed that PKM2 knockdown could lead to a remarkable downregulation of N-cadherin, Vimentin, PKM2, and VEGFA expression in tumor tissues, while E-cadherin expression was notably upregulated." (PMID 38195651, 2024). "Matrix metalloproteinases (MMPs), fibronectin, and vimentin provide valuable insight into the EMT process in OSCC, while their expression may determine the aggressiveness of the tumor and metastasis potential." (PMID 38539520, 2024). "Furthermore, the increased FXR expression was positively correlated with vimentin and SLC7A11 in clinical tumor specimens." (PMID 39543094, 2024). "Other studies compared the expression of mesenchymal markers between single tumor cells and tumor cell clusters in PMP and found that single tumor cells had more obvious EMT status, E-cadherin negativity, and strong vimentin positivity, while cell clusters exhibited contrary results." (PMID 38611084, 2024). "Another study found that glabridin inhibited EMT in breast cancer cells by upregulating E-cadherin and occludin, while downregulating vimentin, E-box-binding zinc finger protein 1 (Zeb1), and other critical EMT markers, thereby exerting a controlling effect on tumor invasion and metastasis." (PMID 39723390, 2024). "Its principle may inhibit the migratory ability of SW1990 cells by down-regulating the expression of Ki67, PCNA, Vimentin, and MMP-9 as well as up-regulating the expression of E-cadherin, thus exerting its anti-tumor effect." (PMID 39193331, 2024). "For example, cells with both GFAP and vimentin have been reported to be more aggressive than vimentin-negative/GFAP-positive tumor cells." (PMID 38295184, 2024). "On immunohistochemical evaluation, the tumor cells were diffusely positive for vimentin, smooth muscle actin, and desmin and negative for S100, CD117, and DOG1." (PMID 39280874, 2024). "The tumor shows the positive expression of immunomarkers Smooth Muscle Actin, Vimentin, and Beta-catenin, while SATB2 is typically negative." (PMID 38378640, 2024). "Immunohistochemistry: Fusiform tumor cells expressed vimentin, epithelial markers were negative, the Ki-67 proliferation index was 40%, and epithelial markers were expressed in squamous intraepithelial neoplasia." (PMID 39686439, 2024). "To identify noncancerous and tumor areas we employed Hematoxylin and Eosin-Y staining (H&E staining) and immunohistochemistry using epithelial and stromal markers (Cytokeratin 8 and Vimentin, respectively)." (PMID 38319971, 2024). "Furthermore, vimentin, PI3K and p-Akt expression was also suppressed in tumor tissue treated with Tan IIA (P < 0.05 and P < 0.001)." (PMID 38297301, 2024). "On immunohistochemical analysis, these tumor cells were positive for CD68 and vimentin." (PMID 38515205, 2024). "Immunohistochemistry showed that the tumor cells expressed cytokeratin 7, P63, P40, CK5/6, Pan Cytokeratin (PCK), and epithelial membrane antigen, whereas they were negative for thyroid transcription factor-1, napsin A, CD10, vimentin, and smooth muscle actin." (PMID 37352028, 2023). "Now it is generally accepted that, although EMT is activated in many cancer types, it is rarely fully executed in tumor cells, and end-stage markers such as vimentin are often not expressed." (PMID 36823234, 2023).